CTHRC1 (collagen triple helix repeat containing 1)
Diseases named in the same sentence as CTHRC1 in open-access papers (continued):
Sharing a sentence is not in itself a finding about the gene and the disease.
COVID-19 (5 papers, 2022 to 2025). A disease caused by infection with severe acute respiratory syndrome coronavirus 2. "In summary, our study shows that progression to fibrosis in severe COVID-19 was associated with overexpression of fibrogenic pathways and increased in CTHRC1- and SPARC-positive pFB." (PMID 36405615, 2022). "Progression to fibrosis in severe COVID-19 is associated with overexpression of fibrogenic pathways and increased in CTHRC1- and SPARC-positive pFBs." (PMID 36405615, 2022). "In the human lung, five fibroblast subtypes have been characterized, including a Collagen Triple Helix Repeat Containing 1+ (CTHRC1+) population that is notably enriched in fibrotic regions of COVID-19 patient lungs." (PMID 40491950, 2025). "The number of CTHRC1-positive pathological fibroblasts was also increased in a study of short postmortem interval specimens from patients with lethal COVID-19." (PMID 38891078, 2024). "There was a statistically significant increase of CTHRC1 expression in COVID-19 samples when compared with control samples." (PMID 36405615, 2022). "An enrichment of COLA31 + /CTHRC1 + pFB has also been observed in some COVID-19 samples." (PMID 36405615, 2022).
endometrial cancer (5 papers, 2020 to 2021). Primary or metastatic malignant neoplasm involving the endometrium (mucous membrane that lines the endometrial cavity). "We also analyzed the CTHRC1 translational level in normal and head and neck, kidney, liver, lung, stomach, and endometrial cancers tissues using HPA." (PMID 34615943, 2021). "CTHRC1 increases the recruitment of M2-like macrophages, prompting myometrial invasion in endometrial carcinoma by regulating the integrin-Akt signaling pathway." (PMID 33363026, 2020). "Besides, the invasion and metastasis of endometrial cancer are closely related to the upregulation of CTHRC1-mediated CX3CR1 in macrophages." (PMID 32848510, 2020). "In addition, CTHRC1 promoted M2-like macrophage recruitment and myometrial invasion in endometrial carcinoma by the integrin-Akt signaling pathway, which indicated that CTHRC1 might be a biomarker for tumor immunotherapy." (PMID 34512711, 2021).
glioma (5 papers, 2020 to 2023). A benign or malignant brain and spinal cord tumor that arises from glial cells (astrocytes, oligodendrocytes, ependymal cells). "Peng at al reported that in addition to being upregulated in high-grade gliomas, CTHRC1 expression correlated with genes associated with the Wnt Signaling pathway (DVL3, DVL1, DVL2, ROR2, WNT3A, FZD6 and FZD5)." (PMID 36190948, 2022). "Using the LinkedOmics online database, we analyzed the genes associated with CTHRC1 in glioma (LGG/GBM), as well as the pathways and functions involved." (PMID 34702252, 2021). "CCLE data of glioma analysis indicated the CTHRC1 mRNA expression level was negatively linked to the CTHRC1 DNA methylation level in both CTHRC1 mRNA expression (Affy and RNA-seq) datasets." (PMID 34702252, 2021). "CTHRC1 mRNA expression was negatively associated with the DNA methylation level in glioma." (PMID 34702252, 2021). "In particular, we focused on the association between CTHRC1 expression and the glioma prognosis." (PMID 34702252, 2021). "CTHRC1 expression in glioma was detected using qPCR to further investigate the level of CTHRC1 expression and its function in glioma." (PMID 34702252, 2021). "Analyses of both the CGGA and TCGA datasets indicated that the CTHRC1 mRNA was consistently upregulated with increasing grade in glioma samples." (PMID 34702252, 2021). "Based on the CGGA cohort, the correlation between the CTHRC1 mRNA expression level and overall survival of patients with different grades of glioma was further analyzed using Kaplan–Meier survival curves and the log-rank method." (PMID 34702252, 2021). "Thirdly, this article lacks the detailed molecular mechanisms of CTHRC1 in tumors, including glioma." (PMID 34702252, 2021). "The analysis of CGGA mRNAseq_325 data showed that patients with glioma presenting higher CTHRC1 expression levels had a worse survival probability than those with lower CTHRC1 expression levels." (PMID 34702252, 2021). "In comparison with our mRNA sequence results, which showed 404 upregulated mRNAs in Lv-HOXA11-AS-infected U87 cells, we found that only CTHRC1, a critical gene promoting tumor progression and metastasis including glioma, overlapped with the let-7b-5p target set (right)." (PMID 36351895, 2022). "Analysis of CTHRC1 expression in 41 glioma samples confirmed these results." (PMID 36351895, 2022). "Then, we downloaded CTHRC1 expression data for glioma from GTEx, TCGA and CGGA datasets." (PMID 34702252, 2021). "qPCR was used to detect CTHRC1 expression in glioma tissues and cell lines." (PMID 34702252, 2021). "Our experimental data further confirmed the reliability of the oncogenic role of CTHRC1 in glioma." (PMID 34702252, 2021). "Thus, in combination with the online database analysis and experimental data, we emphatically investigated the expression of CTHRC1 in glioma tissues and cell lines." (PMID 34702252, 2021). "In addition to the online analysis, we performed qPCR experiments to validate the expression of CTHRC1 in glioma clinical tissue samples and cell lines." (PMID 34702252, 2021). "Therefore, we subsequently investigated the potential correlation between CTHRC1 DNA methylation and the pathogenesis in glioma from TCGA cohort via the MEXPRESS approach." (PMID 34702252, 2021). "At the same time, CTHRC1 was also proven to be expressed at high levels in glioma cell lines compared with normal astrocyte cells, suggesting they might function as oncogenes in gliomas." (PMID 34702252, 2021). "Importantly, we investigated the expression of CTHRC1 in glioma clinical tissues and cell lines using qPCR." (PMID 34702252, 2021). "Similarly, compared with the normal astrocyte cell line, the CTHRC1 expression level was also increased in glioma cell lines, including U87, LN229, U251, A172, and T98G." (PMID 34702252, 2021). "The effect of CTHRC1 on the glioma phenotype requires further experimental identification." (PMID 34702252, 2021).
glioma (continued). "The expression and function of CTHRC1 were also further verified in glioma tissues and cell lines." (PMID 34702252, 2021). "Our previous studies showed that CTHRC1 was overexpressed in various cancer types and functions as an important oncogene that may promote tumorigenesis and development through different mechanisms including glioma." (PMID 36351895, 2022). "RT-qPCR analysis of 41 glioma samples revealed a positive correlation between HOXA11-AS expression and CTHRC1 expression." (PMID 36351895, 2022). "Firstly, this study only verified the expression of CTHRC1 in glioma tissues and cells, but not in other tumors." (PMID 34702252, 2021). "The methylation level of the CTHRC1 promoter in GBM was lower than that in LGG, suggesting that abnormal methylation of DNA promoter may be an important factor for the high expression of CTHRC1 mRNA in glioma." (PMID 34702252, 2021).
invasive breast carcinoma (5 papers, 2012 to 2022). A carcinoma that infiltrates the breast parenchyma. "Recently, it was reported that some human solid tumors, including metastatic melanoma and invasive breast cancer, showed higher expression of CTHRC1." (PMID 24504172, 2014). "Cthrc1 is a Smad2/3 (TGF-β signalling) inhibiting Wnt signalling modulator that is differentially expressed in invasive breast cancer and several solid tumors." (PMID 22260314, 2012). "RNA-seq data extracted from TCGA database showed a consistent trend of abnormally high CTHRC1 expression in more than 16 types of tumour tissues compared with the corresponding normal tissues, such as COAD, breast invasive carcinoma and stomach adenocarcinoma." (PMID 35300110, 2022). "Finally, our results of immunohistochemical staining for CTHRC1 showed that poorly-differentiated HCC had a higher expression level of CTHRC1 compared with well-differentiated HCC, supporting previous findings in invasive breast cancer." (PMID 24841500, 2014).
liver cancer (5 papers, 2020 to 2025). An epithelial or non-epithelial malignant neoplasm that arises from the liver. "Significantly elevated expression levels of CTHRC1 were observed in breast, esophageal, and liver cancers compared to corresponding paraneoplastic tissues." (PMID 40134434, 2025).
pancreatic ductal adenocarcinoma (5 papers, 2014 to 2024). An infiltrating adenocarcinoma that arises from the epithelial cells of the pancreas. "In pancreatic ductal carcinoma, Cthrc1 was localized in some stromal cells surrounding the cancer cells." (PMID 24945147, 2014).
cervical squamous cell carcinoma (4 papers, 2017 to 2023). A squamous cell carcinoma arising from the cervical epithelium. "Stronger CTHRC1 staining was detected in the cervical squamous cell carcinoma tissues and cervical adenocarcinoma tissues than that in CIN and normal cervical tissues." (PMID 28303973, 2017). "Further, we performed an immunohistochemical analysis of CTHRC1 in a tissue microarray containing 101 cervical squamous cell carcinoma tissue samples, 29 cervical adenocarcinoma tissue samples, 19 cervical intraepithelial neoplasia (CIN) and 30 normal cervical tissues." (PMID 28303973, 2017). "POSTN + fibroblasts showed high expression levels of several ECM remodeling genes (MMP11, CTHRC1, COL1A1, COL1A2, COL3A1, COL10A1, and COL11A1) and enriched signatures of ECM, which were consistent with the previously reported matrix CAFs (mCAFs) in cervical squamous cell carcinoma (CESC)." (PMID 37833788, 2023).
oral squamous cell carcinoma (4 papers, 2017 to 2021). "N-Glycosylation stabilizes CTHRC1 in oral squamous cell carcinoma (OSCC) specimens by reducing protein turnover rate, and CTHRC1 is positively feedback-regulated by the DPAGT1/canonical Wnt pathway, thereby activating noncanonical Wnt pathways to drive tumor cell migration and invasion." (PMID 32848510, 2020). "Previous reports have suggested that other mechanisms may be involved in regulation of CTHRC1, such as TGF-β and Wnt3a pathway activation in gastric and oral squamous cell carcinoma, respectively." (PMID 28645305, 2017).
renal cell carcinoma (4 papers, 2016 to 2023). "It was shown that CTHRC1 is highly expressed in renal cell carcinoma tissue, and the knockdown of CTHRC1 was shown to inhibit the proliferation of carcinoma cells as well as negatively affect the epithelial–mesenchymal transition process." (PMID 37109608, 2023). "Based on these observations, up-regulation of HMGA2 and CTHRC1, together with loss of CDKN2A, may serve as prognosis markers in renal cell carcinoma." (PMID 27144525, 2016).
steatosis (4 papers, 2012 to 2023). Increased lipid within the cytoplasm of cells. "We have demonstrated that deletion of the Cthrc1 gene leads to fatty liver (steatosis) formation in mice while others showed that inactivation of this gene also results in low bone mass." (PMID 24945147, 2014). "Livers from CTHRC1 null mice accumulated vast quantities of lipid, leading to extensive macrovesicular steatosis." (PMID 24360150, 2013). "On the C57BL/6J background, livers from Cthrc1 null mice accumulated vast quantities of lipid, leading to extensive macrovesicular steatosis." (PMID 23056600, 2012). "Although, further studies are required to clarify whether CTHRC1 acts as an agonist for GPR180 in the liver, the development of antagonists is needed for the treatment of steatosis." (PMID 36726016, 2023).
thyroid cancer (4 papers, 2020 to 2024). "We provide compelling evidence that CTHRC1 is linked to the BRAF(V600E) mutation in both colon and thyroid cancers, further highlighting the significant role of CTHRC1 in influencing patient prognosis." (PMID 39052013, 2024). "In thyroid cancer patients, significant correlations were found between OS rates and risk factors, including tumor size (HR ═ 3.07) (P ═ 0.038), clinical stage (HR ═ 7.1) (P < 0.001), and CTHRC1 expression level (low and high) (HR ═ 3.03) (P ═ 0.027)." (PMID 39052013, 2024). "A few studies found that there was an aberrant expression of CTHRC1 in thyroid cancers, and CTHRC1 expression levels in PTC were significantly correlated with lymph node metastases, the expression of E-cadherin and vimentin." (PMID 33564303, 2021). "Additionally, the differential expression of CTHRC1 was compared between thyroid cancer (TC) tissues and normal thyroid tissues in the TCGA database, which further confirmed the upregulation of CTHRC1 in TC tissues." (PMID 37273536, 2023). "In thyroid cancer, immune cells (especially neutrophils, dendritic cells, B cells, CD4+ T cells, and macrophages) were also positively correlated with CTHRC1 expression, while Th17 cell infiltration was negatively correlated with CTHRC1 expression." (PMID 39052013, 2024). "Analysis of data from the Gene Expression Omnibus (GEO) and The Cancer Genome Atlas (TCGA) databases showed that collagen triple helix repeat containing-1 (CTHRC1) was specifically upregulated in ATC tissues and was negatively correlated with overall survival (OS) in thyroid carcinoma patients." (PMID 37273536, 2023).
Barrett esophagus (3 papers, 2017 to 2022). Esophageal lesion lined with columnar metaplastic epithelium which is flat or villiform. "Recently, a germline mutation in CTHRC1 gene was identified to be associated with Barrett’s oesophagus and oesophageal adenocarcinoma, and high CTHRC1 expression in ESCC was revealed by expression profiling studies involving a small number of cases." (PMID 28645305, 2017). "As CTHRC1 was found to have the highest HR among other up-regulated hub genes, a nomogram was created based on CTHRC1, age, gender, reflux history, Barrett’s esophagus, H. Pylori infection, pathologic stage, histologic grade, and resident tumor." (PMID 35910202, 2022).
esophageal cancer (3 papers, 2021 to 2024). A primary or metastatic malignant neoplasm involving the esophagus. "In Esophageal Cancer COL3A1 is overexpressed with POSTN which further emphasizes the joint role they could have with CTHRC1." (PMID 36190948, 2022).
gastric tumors (3 papers, 2022). "F04 specifically expressed CTHRC1, which was over-expressed in gastric tumors and associated with poor prognosis." (PMID 35664061, 2022). "Immunofluorescence staining showed that CTHRC1 was present in the vascular tissue surrounding the gastric tumors, suggesting the high interaction for CTHRC1 and blood vascular development." (PMID 35928443, 2022). "Immunofluorescence staining of CTHRC1 showed the location of CTHRC1+ cells was endothelial cell surrounding in gastric tumors." (PMID 35664061, 2022).
head and neck squamous cell carcinoma (3 papers, 2016 to 2024). A squamous cell carcinoma that arises from any of the following anatomic sites: lip and oral cavity, nasal cavity, paranasal sinuses, pharynx, larynx, and salivary glands. "In this study, we systematically analyzed the expression status and prognostic value of CTHRC1 in head and neck squamous cell carcinoma using data from the TCGA and GEO database." (PMID 38937712, 2024). "In this study, we observed that CTHRC1 expression tends to be up-regulated in advanced stages of head and neck squamous cell carcinoma." (PMID 38937712, 2024).
Obesity (3 papers, 2021 to 2025). Accumulation of substantial excess body fat. "Of them, Ctnnd2, Dap, Marchf6, Cmbl, Sdc2, Cpq, Stk3, Vps13b, Cox6c, Grhl2, Fzd6, Cthrc1, Lrp12, and Zfpm2 showed associations or had functions related to atherosclerosis or obesity." (PMID 40362477, 2025). "In an obesogenic context, it would also be important to determine whether specific CTHRC1 gene mutations correlate with human obesity, particularly those mutations that could potentially hamper the anti-adipogenic activity of CTHRC1 or its effectors." (PMID 40076432, 2025). "As with mouse models, it will be important to determine CTHRC1 gene expression trends in white adipose tissue during human development and whether diminished CTHRC1 gene expression in early postnatal development is predictive of juvenile, adolescent, or adult obesity." (PMID 40076432, 2025).
Wilms tumor (3 papers, 2019 to 2023). An embryonal neoplasm characterized by the presence of epithelial, mesenchymal, and blastema components. "We screened four highly expressed m6A-related genes (ADGRG2, CPD, CTHRC1, LRTM2) in nephroblastoma and constructed an effective diagnostic model based on these genes." (PMID 37938417, 2023).
acute myeloid leukaemia (2 papers, 2014 to 2024). "Cthrc1 plasma levels were also significantly elevated during pregnancy, in diabetes, in inflammatory and infectious conditions, acute myeloid leukemia but not solid cancers." (PMID 24945147, 2014).
atherosclerosis (2 papers, 2022 to 2025). A disease characterized by the build-up of fatty material and calcium deposition in the arterial wall resulting in partial or complete occlusion of the arterial lumen. "CTHRC1 is an ECM protein associated with atherosclerosis, and is upregulated in various cancers and involved in several biological functions of tumors, which has value as a potential therapeutic target for cancer." (PMID 35313900, 2022).
bladder cancer (2 papers, 2022). "In this study, we identified six ECM-related genes (CTHRC1, MMP11, COL10A1, FSTL1, SULF1, and COL5A3) that were associated with bladder cancer occurrence, tumor stage, and prognosis based on the bladder cancer tumor samples." (PMID 35450397, 2022). "CTHRC1, MMP11, and COL5A3 protein levels were increased in bladder cancer than in normal bladder samples." (PMID 35450397, 2022). "Based on the TCGA dataset, the expression levels of COL10A1, COL5A3, CTHRC1, MMP11, and SULF1 in the bladder cancer tissues were higher than those in the normal bladder tissues." (PMID 35450397, 2022).
diabetes (2 papers, 2014 to 2021). "In summary, analyses of randomly selected patients show that significantly elevated Cthrc1 levels were found in patients with diabetes, infections or inflammatory and febrile conditions, as well as anemia and leukemia." (PMID 24945147, 2014). "A common theme emerged with the detection of elevated Cthrc1 levels in patients suffering from conditions that have an inflammatory or infectious component, e.g. fever, yeast and urinary tract infections, thrush, etc., and even diabetes can be included in this category." (PMID 24945147, 2014). "Elevated Cthrc1 was also found in patients with diabetes, inflammatory conditions, and infections, but not solid tumors." (PMID 24945147, 2014).
endometriosis (2 papers, 2024 to 2025). The growth of functional endometrial tissue in anatomic sites outside the uterine body. "Wnt protein binding (GOMF) was a significant pathway in our gene set analyses, with five genes overlapping with our biologically-implicated endometriosis gene set: CTHRC1 (mSMR), FZD6 (fibroblast-eSMR), PTPRO (fibroblast-, ovary-, and whole blood-TWAS), RECK (fibroblast-sSMR), and TRABD2A (mSMR)." (PMID 41377979, 2025). "In our omics results, we observed an elevation in the expression of critical fibrosis-associated proteins, including TGFBR1, α-SMA, CTHRC1, FAP, FN1, and 15 collagen proteins, in endometriosis." (PMID 38735939, 2024).
glioblastoma (2 papers, 2018 to 2022). The most malignant astrocytic tumor (WHO grade IV). "Studies have shown that promoting CTHRC1 expression increased the migration and invasion of primary gastrointestinal stromal tumour cells, whereas silencing CTHRC1 expression inhibited the epithelial–mesenchymal transformation of glioblastoma cells." (PMID 35300110, 2022).